RN7SL34P (RNA, 7SL, cytoplasmic 34, pseudogene)
Gene: Miscellaneous RNA gene on chromosome 19 (41,286,424 to 41,286,693, reverse strand). Ensembl gene ENSG00000239868.
Homologues: Orthologues: chimpanzee Metazoa_SRP (100% identical). Paralogues in human: RN7SL2 (80% identical), RN7SL1 (79% identical), RN7SL3 (78% identical), RN7SL444P (78% identical), RN7SL769P (77% identical), RN7SL223P (77% identical), RN7SL126P (76% identical), RN7SL493P (76% identical), RN7SL147P (76% identical), RN7SL326P (76% identical), RN7SL448P (76% identical), RN7SL45P (76% identical), and 703 more.